CDKN2A (cyclin dependent kinase inhibitor 2A)
Diseases named in the same sentence as CDKN2A in open-access papers (continued):
Sharing a sentence is not in itself a finding about the gene and the disease.
melanoma (continued). "For the familiar melanoma CDKN2A gene, 22 variants have been described, 8 of these as likely pathogenic and 10 as uncertain significance." (PMID 33102592, 2020). "The systematic analysis of 80 melanoma-prone families identified 37 distinct mutations affecting the CDKN2A locus." (PMID 33076392, 2020). "Inactivating mutations in the cyclin-dependent kinase inhibitor 2A (CDKN2A) gene result in a dysregulated cell cycle promoting melanoma transformation." (PMID 32079144, 2020). "The most common acquired genetic change distinguishing precursor lesions, such as melanocytic nevi or melanoma in situ (MIS), from invasive melanomas is loss of the CDKN2A locus." (PMID 32894202, 2020). "This c.256G > A CDKN2A variant was detected in one of the brothers and in the melanoma-free mother while the other brother in the family tested negative." (PMID 32760473, 2020). "High-risk CDKN2A mutations significantly contribute to the genetic architecture of melanoma as these are found in about 30% of patients in families of three or more affected individuals." (PMID 32760473, 2020). "The frequency of CDKN2A mutation carriers rose from <40% for patients with three relatives with melanoma to >90% for those with more than six relatives with melanoma." (PMID 33050356, 2020). "A later study confirmed that four frequent MC1R variants (Val60Leu, Val92Met, Arg151Cys, Arg160Tro) were associated with an increased melanoma risk in CDKN2A mutation carriers." (PMID 33076392, 2020). "We will illustrate the genetic literacy problem with a real world example from a melanoma family with a CDKN2A mutation c.256G > A." (PMID 32760473, 2020). "In 2015, a revision of the prevalence of mutations in susceptibility CMM genes reported that, in 2511 melanoma-prone pedigrees, the mutation prevalence was about 20% for CDKN2A, 0.7% for CDK4, 1% for BAP1, and 0.5% for POT1." (PMID 33322357, 2020). "This is the first study in the Colombian population that sought to determine the frequencies of the polymorphic variants of the CDKN2A gene and their implication in the susceptibility of melanoma." (PMID 33102592, 2020). "CDKN2A was identified as the first melanoma susceptibility gene more than 20 years ago, and germline CDKN2A mutations have been found in up to 20–40% of the melanoma-prone families worldwide." (PMID 32605315, 2020). "We present here a real world example of the c.256G > A CDKN2A variant, which was detected in one melanoma patient where two siblings were diagnosed with melanoma in situ." (PMID 32760473, 2020). "Performing germline/tumour whole-exome sequencing of 44 stage III/IV melanoma patients we identified pathogenic germline mutations in CDKN2A, CDK4, ATM, POLH, MRE11A, RECQL4 and XPC, affecting 7/44 patients." (PMID 33077847, 2020). "CDKN2A gene is one of the most frequent tumor suppressors genes altered between 50 and 80% of melanomas; it encodes p16 and p14ARF proteins, which act as negative regulators in the transition of the G1/S and G2 phase of the cell cycle." (PMID 33102592, 2020). "In contrast, in humans the bi-allelic loss of CDKN2A has only been shown to promote melanoma invasion." (PMID 32165639, 2020). "The CDKN2A locus is the most common melanoma-dominant predisposition gene and somatic alterations encompassing this genetic sequence occur early in the development of melanoma." (PMID 33076392, 2020). "Germline mutations in the gene CDKN2A have been found in about 40% melanoma families and CDK4 alterations in 2-3% families." (PMID 32083130, 2020).
melanoma (continued). "The highest prevalence in a subgroup of high-to-moderate melanoma risk genes was found in CDKN2A (NM_000077)." (PMID 33050356, 2020). "About 45% of melanomas have been attributed to germline mutation of predisposition gene CDKN2A, and 2-3% melanomas mutated in gene CDK4 in European and American populations." (PMID 32083130, 2020). "Currently, germline CDKN2A mutations are observed in 20–40% of families with hereditary melanoma across continents." (PMID 31717496, 2019). "(2018) demonstrated that the loss of miR‐204 is common in melanomas with NRAS sole mutation but is less frequent in those harboring CDKN2A mutations." (PMID 30499222, 2019). "Carriers of pathogenic variants in CDKN2A have a 70% life-time risk of developing melanoma and 15–20% risk of developing pancreatic cancer (PC)." (PMID 31203567, 2019). "ANRIL is located in chromosome 9p21, nearby CDKN2A/B genes, and SNPs in this region have been associated with human diseases, e.g. coronary disease, stroke, diabetes, melanoma and glioma." (PMID 30499222, 2019). "CDKN2A mutations lead to uncontrolled cell-cycle progression contributing to the genesis of melanomas." (PMID 31382929, 2019). "Some are well known and strongly associated, like CDKN2A for melanoma, while others are rare (MBD4) or more controversial, like BRCA1/2." (PMID 31382694, 2019). "More than 60 different mutations in the CDKN2A gene were found in hereditary melanoma families, with the majority of them represented by missense mutations in p16." (PMID 31717496, 2019). "Families with glioma and melanoma have in rare cases been observed with germline mutations in CDKN2A/B region." (PMID 31842352, 2019). "ANRIL (antisense non‐coding RNA in the INK4A locus) is a lncRNA first identified in familiar melanoma with CDKN2A/B (INK4B‐ARF‐INK4A) germline mutations." (PMID 30499222, 2019). "Previous studies performed in Ligurian melanoma families showed that founder CDKN2A mutations were prevalent in up to 40% of the cases, leading national scientific societies to recommend genetic testing in high-risk patients for familial CMM." (PMID 31382929, 2019). "Since then, a great amount of studies investigating the role of CDKN2A mutations in the genetic susceptibility of melanoma have been made." (PMID 31382929, 2019). "Considering the global cohort of 16 patients with MPM and family history of melanoma in our series, a CDKN2A mutation was found in the 37.5% of the cases, and thus, only in the 2.3% of the sporadic MPM cases." (PMID 31382929, 2019). "Nevertheless, genetic testing is currently recommended only for CDKN2A mutations in patients with high melanoma risk, including those with MPM." (PMID 31382929, 2019). "Mouse models have revealed a requirement for concurrent loss of CDKN2A/p16, a tumor‐suppressor gene, to develop melanoma." (PMID 30499222, 2019). "Roughly 20% of melanomas have mutations in the CDKN2A gene, and more than 10% mutations of p14ARF (a splice variant of CDKN2A)." (PMID 30987166, 2019). "CDKN2A variants were detected in 46.2% of melanoma-prone families, while a CDK4 variant was found in only one family." (PMID 29774366, 2018). "Two variants located in the 3′UTR, g.124463018 C>T and g.124463400 T>C, were found in early onset patients with multiple primary melanomas each, both tested wild type for CDKN2A mutations." (PMID 29523635, 2018). "The aims of this study were to evaluate CDKN2A/CDK4 variants in Greek familial melanoma patients and to correlate the mutational status with specific clinico-epidemiological characteristics." (PMID 29774366, 2018). "Even though major melanoma predisposing genes such as CDKN2A and CDK4 have been discarded in the MeLiM model, six loci that have been associated with human melanoma show association signals in pigs." (PMID 29963229, 2018).
melanoma (continued). "The CDKN2A gene is frequently mutated or deleted in melanoma tumors, leading to a release in the inhibition of cyclin-dependent kinases CDK4 and CDK6, causing a progression from G1 to S-phase and increased cell cycle activity and proliferation." (PMID 29946532, 2018). "Studies have shown that awareness of CDKN2A variant status among melanoma patients and relatives increases their compliance in sun protection and rigorous mole screening." (PMID 29774366, 2018). "In conclusion, our study delineates the important role of CDKN2A variants in Greek familial melanoma families, as almost half of our studied population carried a disease-causing variant in this gene." (PMID 29774366, 2018). "CDKN2A is responsible for melanoma susceptibility in approximately 10% of 2-case melanoma families and 30–40% of families with 3 or more cases of melanoma up to third-degree relatives, whereas its incidence among sporadic melanomas is very low (less than 3%)." (PMID 29774366, 2018). "Mutations in uORF initiation and termination codons have been linked to human malignancies and a mutation introducing a uORF into the TL of CDKN2A causes familial predisposition to melanoma." (PMID 30067734, 2018). "Familial melanoma is responsible for 8–12% of melanoma cases, being cyclin-dependent kinase inhibitor 2A (CDKN2A) and CDK4 the major susceptibility genes involved in this context." (PMID 30166456, 2018). "Melanoma is the deadliest form of skin cancers and about 10% cases occur in a familial context involving cyclin-dependent kinase inhibitor 2A as a main high-risk gene for melanoma." (PMID 30233358, 2018). "In previous studies, the major predisposition genes for human melanoma were discarded: for example, CDKN2A was excluded thanks to an association and a haplotype analysis." (PMID 29963229, 2018). "Specifically, the mean age at melanoma diagnosis was shifted a decade earlier in carriers of CDKN2A variants, highlighting the need for intense vigilance in these individuals from a young age." (PMID 29774366, 2018). "This study confirmed that, in the Greek population, the age at melanoma diagnosis was lower in patients carrying a variant in CDKN2A compared with wild-type patients." (PMID 29774366, 2018). "Among available DNA samples, the rate of mutations in CDKN2A was much higher in melanoma metastases (11/72; 15.3%) versus primary melanomas (4/54; 7.4%) (data not shown)." (PMID 29492214, 2018). "Among the 52 melanoma-prone families, 24 families (46.2%) were found to have 1 variant of CDKN2A and 2 of these families carried 2 different variants of this gene simultaneously." (PMID 29774366, 2018). "Regarding the genetic background, several susceptibility genes have been identified, including highly penetrative genes such as CDKN2A, the first familial melanoma gene identified which is found mutated in approximately 40% of melanoma high-density families." (PMID 29596374, 2018). "While the human CDKN2A gene is mutated or deleted, which frequently occurred in some malignancies such as melanoma, tumor cells would overcome BRAF V600E-induced senescence and become malignant." (PMID 30111351, 2018). "CDKN2A mutations have been reported in two children affected with WT in a study assessing the risk of non-melanoma cancers in first-degree relatives of CDKN2A mutation carriers." (PMID 30344923, 2018). "In familial melanoma, up to 40% of patients show germline mutations in the CDKN2A gene, hence, CDKN2A is considered the major melanoma susceptibility gene with high penetrance in the south-european area." (PMID 29464027, 2018). "p16 loss of expression in melanoma tissue was found in 10 out of 14 (71%) CDKN2A germline mutated cases, as compared to 45 out of 73 (62%) CDKN2A wild type cases, but this difference was not statistically significant (p = 0.559)." (PMID 29464027, 2018).
melanoma (continued). "Families that carry a pathogenic mutation in CDKN2A have an increased risk for melanoma, pancreatic cancer, and perhaps neurological tumors like astrocytoma." (PMID 28283772, 2017). "Especially in an era when reasonably priced multi-gene panel tests are available, it no longer seems appropriate to offer genetic testing to high-risk melanoma patients for only CDKN2A when other genes are known to cause melanoma-dominant syndromes." (PMID 28283772, 2017). "Early genome‐wide association studies on familial melanoma identified that cyclin‐dependent kinase inhibitor 2A (CDKN2A) was a melanoma risk loci, which encodes two tumor suppressors, P14ARFand P16INK4a." (PMID 28544818, 2017). "For example, as many as 40% of hereditary melanomas can be linked to germline mutations in the cyclin-dependent kinase inhibitor 2A (CDKN2A) gene." (PMID 29900017, 2017). "In fact, CDKN2A germline mutations have been identified in less than 2% of single primary melanoma cases, 8-12% of sporadic MPM cases and 47% of MPM patients with familial melanoma (fM)." (PMID 27776349, 2017). "For instance, it is unclear how environment, other prognostic risk factors such as the hair, eye, and skin color, and/or ethnicity contribute to the overall risk in individuals with CDKN2A (or other melanoma gene) mutations." (PMID 28283772, 2017). "These two tumor suppressors have been most studied in the context of melanoma, likely because germline CDKN2A mutations in some families confer increased melanoma risk." (PMID 28915557, 2017). "Detection of aberrantly methylated SOCS1/2, RASSF1A, MGMT, and CDKN2A in serum has been reported to have diagnostic value in patients with malignant melanoma." (PMID 28396701, 2017). "The most common high-risk gene predisposing to melanoma is CDKN2A, which is also associated with pancreatic cancer." (PMID 28198461, 2017). "CDKN2A gene mutations have been widely reported as the most common cause of inherited susceptibility to melanoma." (PMID 27776349, 2017). "Recently, we described functional germline 5’UTR CDKN2A variants from melanoma patients affecting the post-transcriptional regulation of p16INK4a mRNA that is dependent, at least in part, on an Internal Ribosome Entry Site (IRES) in the 5’UTR region." (PMID 29216274, 2017). "It has been noted that high-penetrance variants found in melanoma-prone families can also contribute to sporadic disease, for example, germline mutations of CDKN2A have been identified in around 2% of cases in European and Australian cohorts." (PMID 28062663, 2017). "In melanoma and non-melanoma skin cancer cells with CDKN2A mutated, IFI44L is also reported upregulated." (PMID 28881752, 2017). "We recently performed functional studies of 5’UTR CDKN2A germline mutations in melanoma patients and identified an Internal Ribosomal Entry Site (IRES)-like activity in the 5’UTR of CDKN2A." (PMID 29216274, 2017). "The re-analysis enabled us to solve one case with an uncertain clinical diagnosis: a whole CDKN2A deletion causing melanoma and neural system tumor syndrome (OMIM: 155755) was identified in the patient with clinical suspicion of NF1 (Sample R2)." (PMID 28051113, 2017). "Germline mutations in the CDKN2A gene are associated with an increased risk of malignant melanoma and pancreatic cancer." (PMID 27804060, 2017). "Using the RCAS/Dct:TVA mouse model of melanoma, we found that gain-of-function MEK1 mutations (V60E, C121S and GF) are capable of transforming melanoma cells in vitro and driving high-grade melanoma in the context of Cdkn2a and Pten loss." (PMID 28263969, 2017). "The case of pancreatic cancers in melanoma families is instructive in this context because CDKN2A is the dominant high-risk gene for both cancers." (PMID 28198461, 2017).
melanoma (continued). "Use of this “rule of twos or threes” criteria for melanoma genetic testing leads to approximately 10% positive results for CDKN2A mutation." (PMID 28283772, 2017). "While some families with germline CDKN2A mutations are prone to development of just melanomas, other families develop both melanomas, astrocytomas, and occasionally other nervous-system neoplasms including peripheral nerve sheath tumors and meningiomas." (PMID 28699883, 2017). "After eliciting a prior history of multiple primary melanomas and breast cancer, she was tested for and shown to be a carrier for a germline mutation in CDKN2A." (PMID 29110637, 2017). "Another RAS mutation, NRasQ61K, in melanocytes induced melanoma development with a low incidence rate and only after a long latency; cross-breeding with CDKN2A knockout mice increased the incidence of melanomas, with a reduced latency period." (PMID 29156643, 2017). "Genetic mutations have been identified in melanoma prone families including mutations in cyclin kinase 2A (CDKN2A) and cyclin kinase 4 (CDK4) genes, both of which encode proteins involved in the retinoblastoma pathway." (PMID 26938746, 2016). "The occurrence of multiple primary melanomas is associated with family history, dysplastic nevus syndrome, and the germline CDKN2A." (PMID 27022491, 2016). "Mutations in cyclin-dependent kinase inhibitor 2A (CDKN2A) is common among human cancers including melanoma." (PMID 27941674, 2016). "MC1R variants can modify the penetrance of CDKN2A mutations, as carriers of mutations in both genes are at increased risk of developing malignant melanoma compared to individuals carrying a mutation in only one gene." (PMID 26938746, 2016). "These are only present in about 2% of a population of melanoma patients, but for melanoma patients with a family history of melanoma 20% to 60% are carriers of mutations in either CDKN2A or CDK4." (PMID 27022491, 2016). "For individuals carrying germline mutations in CDKN2A, the risk of developing melanoma before the age of 80 has been estimated to be 67 %." (PMID 27519597, 2016). "Review of 13 additional patients with pathogenic CDKN2A variants suggested associations of germline CDKN2A mutations with an expanded spectrum of non-melanoma familial cancers." (PMID 29263814, 2016). "The CDKN2A is the primary familial high-risk melanoma susceptibility locus identified in families with different cases of melanoma." (PMID 27833586, 2016). "For example, a pathogenic donor splice site mutation in the tumor suppressor gene MEN1 is responsible for the retention of intron 9, while a mutation of a splice acceptor site in CDKN2A causes exon skipping in melanoma patients." (PMID 26992833, 2016). "Our analogs should also benefit individuals who are carriers of mutations in other melanoma predisposition genes, such as CDKN2A." (PMID 27582758, 2016). "Germline CDKN2A mutations occur in 40 % of 3-or-more case melanoma families while mutations of CDK4, BAP1, and genes involved in telomere function (ACD, TERF2IP,POT1), have also been implicated in melanomagenesis." (PMID 26433962, 2016). "CDKN2A mutation carriers tend to have multiple primary melanomas, early onset melanoma and an increased risk of developing pancreatic cancer and have also been shown to have an increased risk of tobacco associated cancers in respiratory and digestive tissues." (PMID 26433962, 2016). "Worldwide, CDKN2A mutations explain predisposition in approximately 40 % of families with three or more cases of melanoma, ranging from 20 % in Australia to 57 % in Europe." (PMID 26433962, 2016). "The deletion of CDKN2A and loss of p16INK4A protein was shown to predict sensitivity of melanoma cell lines to Palbociclib, while loss of RB1 led to drug resistance." (PMID 27409346, 2016). "In our patient with hemizygous germline deletion of CDKN2A, it is prudent to extend melanoma screening given the increased risk of melanoma in families with CDKN2A alterations." (PMID 29263814, 2016).